EEF2K (eukaryotic elongation factor 2 kinase)
Diseases named in the same sentence as EEF2K in open-access papers (continued):
Sharing a sentence is not in itself a finding about the gene and the disease.
cancer (continued). "Due to eEF2K’s implications in a variety of disease pathways, A-484954 serves as an exciting tool to alter elongation control in a variety of unhealthy states as has been demonstrated in cardiovascular sciences in vivo and cancer studies in vitro." (PMID 36770760, 2023). "In addition, eEF2K plays a significant role in several diseases, including neurodegenerative diseases, cancer, cardiovascular diseases, muscular hypertrophy, and other immune pathologies." (PMID 38071243, 2023). "Eukaryotic elongation factor-2 kinase (eEF2K) is a potential therapeutic target for cancer." (PMID 35050002, 2022). "It was shown that EEF2K is activated and overexpressed in many cancers." (PMID 36601599, 2022). "It is worth noting that the observed inhibitory Ser366 phosphorylation of eEF2K may limit cancer cell migration and metastasis, although an increased metastatic growth has been reported for a number of cancer types with the active ghrelin-GHSR axis." (PMID 35841486, 2022). "Therefore, eEF2K is considered as a new potential target for cancer therapy, and the research and development of eEF2K inhibitors are of great clinical significance." (PMID 35956836, 2022). "Targeting EEF2K inhibited key parts of the cholesterol pathway in cancer cells, which could be rescued by the addition of exogenous cholesterol, suggesting that it is a potentially important pathway modulated by targeting this process." (PMID 35408842, 2022). "Studies have shown that miR-603 directly targets eEF-2K in cancer cells." (PMID 35682990, 2022). "In addition, a summary of progress for in vitro eEF2K inhibitors from anti-cancer drug discovery research in recent years, along with their structure–activity relationships (SARs) and synthetic routes or natural sources, is also described." (PMID 33673713, 2021). "Additionally, the design and synthesis of purposeful multi-target inhibitors of eEF2K with other relevant anti-cancer targets is also an important research direction for eEF2K inhibitors." (PMID 33673713, 2021). "Therefore, eEF2K is considered a potential drug target for numerous diseases, including cancers, neurodegenerative diseases, cardiovascular diseases, and other immune pathologies." (PMID 34532346, 2021). "Previous studies have demonstrated that eEF2K induces autophagy to protect cancer cells survival." (PMID 33673713, 2021). "Studies showed that rottlerin suppressed the eEF2K gene and protein expression in cancer cells." (PMID 35010954, 2021). "Furthermore, a summary of recent research progress on eEF2K inhibitors for cancer chemotherapy is presented along with the detailed structure–activity relationships (SARs) and synthetic routes or natural sources of existing eEF2K inhibitors." (PMID 33673713, 2021). "The expression of eEF2K can inhibit apoptosis and promote cancer cell survival." (PMID 33673713, 2021). "Moreover, combined inhibition of eEF2K and the protein translation initiation inhibitor, 4EBP1, synergizes to suppress cancer growth, suggesting that excessive protein translation or induction of incompatible signalling pathways is lethal." (PMID 33911160, 2021). "However, the role of eEF2K in cancer is context-dependent; in some cancers types, the increased eEF2K activity has been shown to inhibit translation, allowing cancer cells to adapt to stressful conditions." (PMID 34247201, 2021). "This has led to the hypothesis that eEF2K could act as a ‘double-edged sword’, with cancer-cell-type-specific functions." (PMID 32298235, 2020). "However, the role of eEF2K in cancer development was reported paradoxically and remains to be elucidated." (PMID 32054489, 2020). "Collectively, studies of eEF2K in cancer have revealed some vulnerabilities that may allow targeting of this pathway for therapeutic benefit." (PMID 32298235, 2020). "It was shown that eEF2K controls the switch between autophagy and apoptosis in cancer cells." (PMID 32059483, 2020).
cancer (continued). "However, eEF2K was recently revealed to impact in opposing ways on cancer development depending on the stage and probably the type of cancer, suggesting that it is necessary to learn more about the role of eEF2K in oncology." (PMID 32054489, 2020). "In addition, the decrease in ATP in eEF-2K knockdown cells was reported by our study that eEF-2K promotes the Warburg effect in cancer cells." (PMID 33144562, 2020). "In addition, the eEF2K/eEF2 pathway has been shown to control stress-induced autophagy and apoptosis in cancer cells." (PMID 32059483, 2020). "eEF2K is also important for cancer cell migration and metastasis." (PMID 32298235, 2020). "Our data showed that disruption of eEF-2K could significantly devastate cancer cell’s capacity to flourish after treatment with rapalogs by regulating cell cycle arrest." (PMID 33144562, 2020). "Thus, eEF2K acts downstream of TAp73 to allow translational reprogramming and adaptation to oxidative stress, thereby enhancing cancer cell survival." (PMID 32298235, 2020). "The dysregulation of EEF2K and its clinical relevance have been documented in other cancer types." (PMID 31266475, 2019). "From a therapeutic perspective, development of novel eEF2K inhibitors is actively being pursued towards novel experimental therapies in cancer due to its role in metabolic adaptations in cancer cells for survival under nutrient deprivation, including nervous system malignancies." (PMID 29961428, 2018). "Cancer cells exposed to cytotoxic agents may initiate protective autophagy by activating AMPK, GSK3β, ERK1/2 and eEF2K pathways, and autophagy inhibition may enhance the cytotoxicity of anti-cancer agents." (PMID 28978086, 2017). "Several recent studies have suggested that eEF2K aids cell migration and may thereby play important roles in promoting cancer progression." (PMID 29186827, 2017). "In the past few years, eEF2K has been regarded as a potential cancer target." (PMID 29050305, 2017). "It has been demonstrated that the inhibition of eEF2K sensitizes cancer cells to chemotherapy." (PMID 29050305, 2017). "It seems paradoxical that proliferating cells should express high levels of a negative regulator of protein synthesis, and may suggest that eEF2K has a beneficial effect in cancer cells." (PMID 29186827, 2017). "However, even though it is a negative regulator of protein synthesis, eEF2K is activated and overexpressed in many cancers, suggesting a protective role of eEF2K in cancer cell survival." (PMID 29186827, 2017). "mTORC1 signalling, a negative regulator of eEF2K, is activated in a high proportion of cancers, leading to the idea that inhibiting mTORC1, using rapamycin or related compounds, may be an effective anti-cancer therapy." (PMID 26795954, 2016). "However, several studies using other cancer cell lines have reported that eEF2K promotes autophagy and thereby aids cell survival during nutrient starvation." (PMID 26795954, 2016). "Recent work has identified eukaryotic elongation factor 2 kinase (eEF2K) as playing a key cytoprotective role in cancer cells under conditions of nutrient starvation, implying that inhibiting its activity may offer a novel therapeutic avenue in oncology." (PMID 26795954, 2016). "eEF2K is required for growth and is elevated in many types of cancer (Silveraet al, 2010)." (PMID 25330770, 2014). "For example, a recent assessment of eEF-2K by siRNA-mediated knockdown as well as by a moderately potent ATP-competitive inhibitor of eEF-2K suggested that the contribution of eEF-2K to the proliferation of several common cancer cell lines is minimal." (PMID 22911754, 2012). "Hence, ethyl 1‐(2‐(3,4‐dimethylphenyl)−4‐(3‐fluorobenzyl)−3,5‐dioxo‐2,3,4,5‐tetrahydro‐1,2,4‐triazine‐6‐carbonyl)piperidine‐3‐carboxylate (L15, also named as compound C1), as the most potent eEF2K modulator, was selected to further investigate its mode of action and potential anti‐cancer activity." (PMID 38084501, 2024).
cancer (continued). "Thus, it was suggested that inhibition of eEF2K may be therapeutically beneficial as this would impair cancer cell survival." (PMID 35513296, 2022). "Our findings define a novel mechanism underlying the regulation of cancer cell proliferation by eEF2K independent of its role in protein synthesis, disclosing the diverse roles of eEF2K in cell biology, which lays foundation for the development of new anticancer therapeutic strategies." (PMID 32054489, 2020). "The activity of eEF-2K is increased in rapidly proliferating malignant cells, is inhibited during mitosis, and may contribute to the promotion of autophagy in response to anti-cancer therapies." (PMID 22911754, 2012). "This structural combination allows the design of compounds capable of modulating key cancer-related targets such as S1PR1, CYP26A1, APN/CD13, and eEF2K, supporting the structure–activity relationship approach." (PMID 40807478, 2025). "Indeed, we previously showed that eEF2K protects mammalian cells as well as the nematode worm Caenorhabditis elegans (C. elegans) from nutrient depletion by blocking translation elongation, and that this pathway is exploited by cancer cells during their adaptation to such metabolic stress." (PMID 39003251, 2024). "This study not only generates a powerful research tool to investigate the therapeutic potential of targeting eEF2K, but also provides a promising lead compound for developing novel drugs for the treatment of TNBC and other cancers." (PMID 38084501, 2024). "Our study demonstrates the potential of new small‐molecule degraders of eEF2K as anticancer agents for the treatment of TNBC and other types of cancer." (PMID 38084501, 2024). "EEF2K gene expression was higher in BRCA, LUAD, CHOL, HNSC, KIRC, KIRP, and LIHC cancer tissues than normal tissues and lower in BLCA, COAD, KICH, LUSC, PRAD, STAD, and UCEC cancer tissues." (PMID 39592671, 2024). "In agreement with our results, all the studies showed that ZEB1‐circRNAs are upregulated in cancer; however, they identified different targets and functional axes (miR‐337‐3p/TGFBR1, mR‐195‐5p/LOXL2, miR‐448/EEF2K, miR‐200a‐3p/CDK6 and miR‐199a‐3p/PIK3CA)." (PMID 37408496, 2023). "Moreover, NF‐κB inhibition could decrease EEF2K expression in different cancer cell lines." (PMID 35184394, 2022). "This compound showed low micromolar in vitro cytotoxicity against a variety of cancer cell lines and strongly inhibited both target kinases (PLK1 IC50 = 0.085 μM and eEF2K IC50 = 0.762 μM)." (PMID 33673713, 2021). "Additionally, eEF2K may actively participate in rerouting metabolic pathways in cancer." (PMID 32298235, 2020). "eEF2K maintains the expression of the pyruvate kinase isoform PK-M2 (also known as PKM), which promotes the switch to Warburg metabolism in cancer cells." (PMID 32298235, 2020). "Here, using a phosphoproteomics screen, we found that eEF2K, a kinase involved in the regulation of translation elongation, mediates sensitivity to cotreatment with PI3K and MAPK pathway inhibitors in different cancer types." (PMID 35513296, 2022). "As protein translation is an energy- and resource-consuming cellular process, it is not surprising that EEF2K is overexpressed in cancers as a mechanism to increase protein synthesis." (PMID 35408842, 2022). "Earlier studies, however, did find that blocking the function of eEF2K can effectively kill cancer cells without affecting normal cells." (PMID 33673713, 2021). "The prognostic role of EEF2K expression in these cancer types also warrants further investigation to support the notion." (PMID 31266475, 2019).
cancer (continued). "Interestingly, cancer exosomes triggered a time-dependent bi-phasic effects on TSC22D3 and EEF2K gene expression whereby at 24 h incubation, they were dose-dependently upregulated but were then downregulated at 48 h incubation with cancer exosomes." (PMID 30008265, 2018). "Although eEF2K is highly up-regulated in various cancers, the mechanism of gene regulation has not been elucidated." (PMID 26918606, 2016). "Progress in understanding the physiological functions of eEF-2K and assessing it as a therapeutic target in appropriate in vivo cancer models have been hampered by the lack of potent pharmaceutical agents selective for eEF-2K." (PMID 22911754, 2012). "However, independent of both AMPK and mTORC1, eEF2K activation was also shown to lead to decreased protein synthesis and subsequent cancer cell death." (PMID 37425300, 2023). "Eukaryotic elongation factor 2 kinase (eEF2K or Ca2+/calmodulin-dependent protein kinase, CAMKIII) is a new member of an atypical α-kinase family different from conventional protein kinases that is now considered as a potential target for the treatment of cancer." (PMID 33673713, 2021). "We revealed that PKM2, eEF2K and STAT3 formed a complex and that STAT3 phosphorylation was correlated with expression of c-Myc, a well-known STAT3 target gene and a key contributor to the Warburg effect in most cancer types, leads to both increased aerobic glycolysis and proliferation." (PMID 32054489, 2020). "The role of eEF2K in cancer development has been studied extensively; however, there is no current consensus as to whether eEF2K is beneficial or detrimental to cancer cell survival." (PMID 32298235, 2020). "In addition, in cancer cells, ER stress-induced activation of ATF4 downstream of eIF2α phosphorylation was reported to promote autophagy by activating DDIT4, which in turn increases eEF2K activity through mTOR inhibition." (PMID 32059483, 2020). "However, it is not clear which mechanism accounts for the activation of eEF2K in this type of cancer." (PMID 29186827, 2017). "However, specific eEF2K inhibitors with potent anti‐cancer activity have not been available so far." (PMID 38084501, 2024). "Thus, the critical role of eEF-2K in upholding the activity and function of CTLs warrants further investigation to assess whether therapeutic augmentation of this kinase can be exploited as a novel approach to reinforcing CAR-T therapy against cancer." (PMID 35108044, 2022). "Thus, eEF-2K is critically required for sustaining the viability and function of cytotoxic CD8+ T cells, and therapeutic augmentation of this kinase may be exploited as a novel approach to reinforcing CAR-T therapy against cancer." (PMID 35108044, 2022). "Interestingly, cancer exosomes, but not normal exosomes, modulated expression of matrix remodelling (EFEMP1, DDK3, SPARC), cell cycle (EEF2K), membrane remodelling (LAMP2, SRPX), differentiation (SPRR2E), apoptosis (CTSC), transcription/translation (KLF6, PUS7)." (PMID 30008265, 2018).
neurodegenerative disease (10 papers, 2018 to 2024). A disorder of the central nervous system characterized by gradual and progressive loss of neural tissue and neurologic function. "Given the fact that it functions in protein synthesis and has previously been implicated in other neurodegenerative diseases, EEF2K is an interesting candidate." (PMID 31594549, 2019). "Together, the findings may contribute to our understanding of the molecular mechanisms underlying AD pathogenesis, indicating that suppression of eEF2K activity could be a beneficial therapeutic option for this devastating neurodegenerative disease." (PMID 36158543, 2022). "Pharmacological eEF2K inhibition remains an active area of interest for therapeutic discovery in oncology; however, the therapeutic potential of this approach in neurodegenerative diseases remains largely untapped." (PMID 34092244, 2021). "We anticipate that our findings will stimulate further mechanistic studies and a careful evaluation of eEF2K inhibition in PD, and potentially other neurodegenerative diseases." (PMID 29961428, 2018).
infection (4 papers, 2021 to 2025). The state of being infected such as from the introduction of a foreign agent such as serum, vaccine, antigenic substance or organism. "To evaluate the role of eEF-2K in memory T cell formation, we analyzed WT and eEF-2K−/− mice at day 35 post-infection." (PMID 39861816, 2024). "For example, infection of human gastric adenocarcinoma (AGS) cells with wild-type or the cytotoxin-associated gene A (CagA) and virB7 mutants of H. pylori suppressed eEF2 phosphorylation at Thr-56 on eEF2K at 1 to 3 hours post-infection." (PMID 34532346, 2021). "Our findings suggest that EEF2K, a host kinase that phosphorylates multiple NiV proteins including the fusion glycoprotein, nucleocapsid, and phosphoprotein may regulate infection by targeting key residues in these viral proteins." (PMID 41424949, 2025). "Our study provides evidence that this dephosphorylation might be mediated by PP1 and suggests a novel layer of AMPK regulation by inhibition of the AMPK/EEF2K/EEF2 axis via PP1 starting very early in infection." (PMID 34335531, 2021). "Moreover, several studies have reported the importance of eEF2K in controlling metabolic processes in immunity both during infection and in autoimmune disorders." (PMID 34532346, 2021). "Interestingly, eEF2K expression was also significantly increased in the natural host AGM animals as early as 10 days after infection." (PMID 34532346, 2021). "The kinase-substrate phosphomotif pattern analysis revealed several kinases, including EEF2K, HASPIN, MAPK9, MAST2, and Spleen tyrosine kinase (SYK), that can phosphorylate multiple NiV proteins at various sites, suggesting regulatory roles during infection." (PMID 41424949, 2025). "EEF2K knockdown also showed a trend to reconstitute viral titers late in infection, but this was not statistically significant." (PMID 34335531, 2021).
blood cancer (1 paper, 2021). "We have shown that in mouse models of CRC the molecular mechanism by which normal levels of RPL24 maintain translation is via eEF2K and P-eEF2, therefore implicating this pathway in these previously studied blood cancer models." (PMID 34895463, 2021). "We also speculate as to the role of eEF2K in the previously published blood cancer models where RPL24 depletion was beneficial." (PMID 34895463, 2021).
neurodevelopmental disorder (1 paper, 2022). A behavioral and cognitive disorder with onset during the developmental period that involves impaired or aberrant development of intellectual, motor, or social functions. "Given that alteration in Akt pathway is known to be involved in the pathogenesis of neurodevelopmental disorders, our data might suggest that the restored level of phosphorylated Akt might contribute to the rescue of the behavioral alterations observed in the Scn1a ± mice after eEF2K deletion." (PMID 34980259, 2022).
EEF2K also shares sentences with these, for which no sentence is quoted: Parkinson disease (5 papers); cardiovascular diseases (3); ductal pancreatic carcinoma (2); liver cancer (2); nasopharyngeal carcinoma (2); Obesity (2); alcohol (1); Anxiety (1); bladder urothelial carcinoma (1); brain disorder (1); central nervous system diseases (1); Cerebral ischemia (1); cleft lip (1); esophageal cancer (1); experimental autoimmune encephalomyelitis (1); gastric ulcer (1); hematological cancers (1); Hodgkins lymphoma (1); Immunodeficiency (1); Lewis lung carcinoma (1); malignant glioma (1); medulloblastoma (1); meningioma (1); mental disorder (1); metastatic tumor (1); multiple myeloma (1); neurological disorders (1); prostate carcinoma (1); rectal adenocarcinoma (1); renal cell carcinoma (1).
A further 3 diseases each share a sentence with EEF2K in 1 paper.